ZWINT (ZW10 interacting kinetochore protein)
Diseases named in the same sentence as ZWINT in open-access papers (continued):
Sharing a sentence is not in itself a finding about the gene and the disease.
lung squamous cell carcinoma (3 papers, 2021 to 2023). "Finally, CDK1, PLK1, PCNA, ZWINT and NDC80 identified as hub genes for underlying molecular mechanisms of lung squamous cell carcinoma lymphatic metastasis." (PMID 37185598, 2023). "Finally, CDK1, PLK1, PCNA, ZWINT and NDC80 identified as hub genes for underlying molecular mechanisms of lung squamous cell carcinoma and lymphatic metastasis." (PMID 37185598, 2023). "Further, these researchers combined the clinical and survival follow-up data from TCGA to confirm that high ZWINT expression is associated with poor prognosis in patients with LUAD but not in patients with lung squamous cell carcinoma (LUSC)." (PMID 34852139, 2021).
melanoma (3 papers, 2007 to 2024). A malignant, usually aggressive tumor composed of atypical, neoplastic melanocytes. "have shown that ZWINT may affect the proliferation and migration of melanoma cells by regulating the expression of c-Myc." (PMID 37091844, 2023). "Mechanistically, ZWINT knockdown decreases the protein expression levels of c-MYC, MTOR, phosphorylated MTOR, pp38, and fibronectin, while c-MYC overexpression reversed the effects on melanoma cell proliferation and migration." (PMID 38950330, 2024).
prostate carcinoma (3 papers, 2024 to 2025). A carcinoma that arises from epithelial cells of the prostate gland. "ZWINT has been associated with tumor metastasis, and upregulation has been demonstrated to support cell migration and invasion in multiple malignancies, such as cervical and prostate cancers." (PMID 40650307, 2025). "ZWINT is a target of AR which is upregulated in PCa, and it has been also identified with bioinformatics tools as a hub gene in prostate cancer." (PMID 38542079, 2024).
adrenocortical carcinoma (1 paper, 2021). "ZWINT and CDK1, which correct erroneous centromere-microtubule attachment and regulate the mitotic spindle checkpoint, are mainly involved in cell cycle control in adrenocortical carcinoma." (PMID 34671679, 2021).
bladder cancer (1 paper, 2012). "Moreover, a previous study has shown that a high expression of ZWINT is associated with a poor prognosis in pulmonary carcinomas, thus the up-regulation of ZWINT could also be associated with a poor prognosis for bladder cancer." (PMID 22724020, 2012).
cervical cancer (1 paper, 2018). A primary or metastatic malignant neoplasm involving the cervix. "Capitalizing upon and targeting Minichromosome maintenance protein complex - specifically the MCM2, MCM4 and MCM6 subunits, ZWINT and CDC7 for experimental validation, may provide valuable insights in understanding and detection of progressing cervical neoplasia to cervical cancer at an early stage." (PMID 30150654, 2018).
colorectal cancer (1 paper, 2020). A primary or metastatic malignant neoplasm that affects the colon or rectum. "A comprehensive analysis of mRNAs regulated by hnRNP A0 and immunostaining revealed that mitotic events were regulated by the hnRNPA0-RAB3GAP1 mRNA-mediated ZWINT-1 stabilization in colorectal cancer cells, but not in non-tumorous cells." (PMID 32303675, 2020).
dengue (1 paper, 2025). "However, the identification of novel genes like ZWINT suggests new avenues for research into the molecular mechanisms of Dengue fever." (PMID 40100920, 2025). "While several genes consistently identified dysregulated in dengue patients, such as CXCL10, ZWINT, BUB1, AURKA, STAT1, etc. there was a notable variability in gene expression patterns across the datasets." (PMID 40100920, 2025).
endometriosis (1 paper, 2022). The growth of functional endometrial tissue in anatomic sites outside the uterine body. "Thus, we consider that ZWINT may play a crucial role in the pathogenesis of EMS, but further research is needed to explore its role and potential mechanism in the pathogenesis of endometriosis." (PMID 35585523, 2022).
esophageal cancer (1 paper, 2021). A primary or metastatic malignant neoplasm involving the esophagus. "However, the regulatory mechanism and function of ZWINT expression in esophageal cancer are not completely clear." (PMID 34852139, 2021).
myeloma (1 paper, 2021). "Interestingly, this PHF19 high myeloma cell subtype also exhibited high expression of genes involved in cell cycle including HELLS, EZH2, TYMS, ZWINT, and MKI67." (PMID 34857028, 2021). "Interestingly, this PHF19high myeloma cell subpopulation seems to be the cell cycling fraction as they also exhibited high expression of genes involved in cell cycling including HELLS, EZH2, TYMS, ZWINT, and MKI67." (PMID 34857028, 2021).
oral cancer (1 paper, 2025).
pan (1 paper, 2023). "Therefore, the expression of the ZWINT gene in pan cancer and the possible functions of NSCLC were examined." (PMID 37091844, 2023).
prostate adenocarcinoma (1 paper, 2024). "A differential survival analysis carried out with GEPIA showed the correlation of ZWINT, CDK1, IGFPB3, and TYMS expression with disease-free survival (DFS) in a database of patients with prostate adenocarcinoma." (PMID 38542079, 2024).
stomach adenocarcinoma (1 paper, 2022). "Finally, pan-cancer mutation analysis showed that FAM111B and ZWINT had the highest mutation rates in u corpus endometrial carcinoma and stomach adenocarcinoma, respectively." (PMID 35406786, 2022).
tumor (33 papers, 2012 to 2025). "The association between ZWINT expression and patient prognosis, its potential role in tumor immunity, the clinical features of pan cancer, and the important pathways in cancer were determined using R." (PMID 37091844, 2023). "For both LUAD and LUSC patients, the expression of the ZWINT gene was significantly associated with the tumor stage." (PMID 37091844, 2023). "Similarly, the expression levels of RRM2 and ZWINT have been reported to be associated with tumor formation." (PMID 35028418, 2022). "Interestingly, LMNB1, RACGAP1, TK1, and ZWINT were all positively associated with tumor purity." (PMID 31306099, 2019). "The results from RNA-seq data showed that ZWINT expression was also higher in metastatic tissues (Q1–Q3: 316.5–1273.5, n = 7) and tumor tissues (Q1–Q3: 467–1210, n = 1097) than in normal controls (Q1–Q3: 92–210, n = 112) (P = 1.01E−53)." (PMID 40591167, 2025). "Aberrant ZWINT expression has been detected in diverse tumor tissues, as well as in patient peripheral blood and saliva samples." (PMID 40591167, 2025). "In the future, further investigation is needed to clarify the signaling pathways through which ZWINT mediates tumor growth, invasion, and migration." (PMID 40591167, 2025). "The results from gene chip data showed that ZWINT expression was higher in metastatic tissues (Q1–Q3: 967–2512, n = 7569) and tumor tissues (Q1–Q3: 1045–2346, n = 82) than in normal controls (Q1–Q3: 395–1200, n = 242) (P = 1.06E−51)." (PMID 40591167, 2025). "Beyond its role in cell division, mounting evidence indicates that ZWINT is critical for tumor cell invasion and proliferation." (PMID 40591167, 2025). "In particular, we postulate that the AFAP1-AS1 regulates tumor progression through the miR-508/ZWINT axis." (PMID 40650307, 2025). "A significant positive correlation between the ZWINT gene and pyrimidine metabolism was observed in all types of tumor tissues." (PMID 37091844, 2023). "A complex regulatory relationship was observed between the ZWINT gene and the classical metabolic pathways of the tumor." (PMID 37091844, 2023). "Above all, ZWINT expression was found to be significantly correlated with tumor immune-related pathways, metabolism-related pathways, and cell death-related pathways." (PMID 37091844, 2023). "Four hub genes, including TTK, BUB1B, NUSAP1, and ZWINT, were revealed as tumor-promotive factors in OC, having the potential to be utilized as novel biomarkers and therapeutic targets for OC management." (PMID 37304238, 2023). "To further inquire the expression of NUSAP1 and ZWINT in the (NAFLD)-associated HCC patients, we downloaded the data set GSE164441 including 10 paired NAFLD-associated HCC tumor and adjacent normal tissues." (PMID 35431924, 2022). "Seven pairs of tumor and adjacent non-tumorous tissues were selected to verify the expressions of the ZWINT, RRM2, NDC80, KIF4A, CEP55, CENPU, and CENPF genes." (PMID 35028418, 2022). "It was found that the expression of NUSAP1 and ZWINT was significant higher (p < 0.05) in tumours specimens compared with para-cancer tissues." (PMID 35431924, 2022). "CDK1 expression can be modified by ZWINT to promote HCC progression with increased tumor size and number." (PMID 35681641, 2022). "We next performed qRT-PCR assay using 16 pairs of PC and adjacent non-tumor tissues and found that ZWINT mRNA was highly expressed in PC tissues." (PMID 34900978, 2021). "The average expression of ZWINT was increased in PC tissues compared with levels in nearby non-tumor tissues." (PMID 34900978, 2021). "ZWINT expression was positively related to tumor size, differentiation and Vessel invasion in PC tissues." (PMID 34900978, 2021).
tumor (continued). "Together these data indicate that ZWINT is transcriptionally upregulated by HIF1α in the hypoxic tumor micro-environment." (PMID 34900978, 2021). "In this study, we focused on the mechanism of ZWINT, the interacting proteins and the downstream pathways involved in tumor regulation." (PMID 34900978, 2021). "In this study, we demonstrated that ZWINT, a centromere complex component, was significantly upregulated in PC tumor tissues and high expression of ZWINT was related to poor outcome in PC." (PMID 34900978, 2021). "Previously, ZWINT knockout was found to inhibit the migration, apoptosis, and colony formation of cancer cells while its downregulation reduced tumor volume." (PMID 34852139, 2021). "In summary, CDCA5, FOXM1, KIF15, MCM2, and ZWINT was involved in cell mitosis and supported our research results by affecting the cell cycle regulation of tumor pathogenesis." (PMID 31708970, 2019). "Several miRNAs, such as miR-127-3p and miR-1, have been found to directly or potentially target ZWINT and promote tumor progression." (PMID 31695969, 2019). "Such dysregulation may contribute to accelerated tumor growth and progression, making ZWINT an attractive therapeutic target." (PMID 40591167, 2025). "The activation of epithelial-mesenchymal transition (EMT) induced by ZWINT might be responsible for tumor progression." (PMID 37091844, 2023). "Thus, the exclusion ZWINT intron in the tumour samples is predicted to lead to higher levels of total ZWINT expression, consequent elevation of cyclin D1 and E1 and cyclin dependent kinase 4 expression and promotion of cell proliferation." (PMID 37924098, 2023). "Tumor weight and volume from cells with knockdown of ZWINT were reduced compared with controls." (PMID 34900978, 2021). "Many reports show that ZWINT is a predictor of tumor development." (PMID 33784984, 2021). "ZWINT protein is shown to be elevated in HCC tissues and is associated with tumor size and number." (PMID 33102593, 2020). "In addition, differential analysis from the ONCOMINE online database of tumor and normal tissue in two cohorts indicated that ZWINT, PRC1, CDKN3, CDK1 and CCNA2 were highly expressed in ACC samples." (PMID 31572440, 2019). "However, a study conducted in post-surgery HCC patients showed that ZWINT expression was decreased in tumor samples." (PMID 31695969, 2019). "Similarly, KIF4A, ZWINT, and UBE2C are involved in cell cycle regulation, cell proliferation, and mitosis, with frequent dysregulation observed in cancers and a clear association with tumor progression and poor clinical outcomes." (PMID 39684488, 2024). "It was suggested that FAM111B and ZWINT may promote tumor proliferation through the EMT process." (PMID 35406786, 2022). "It intimated that FAM111B and ZWINT may promote tumor spread through the EMT process." (PMID 35406786, 2022). "Further analysis of oncogenes and tumor suppressor genes revealed that tumors exhibited elevated expression of oncogenes such as ZWINT and ZIC4, and decreased expression of tumor suppressors like HAMP and CXCL14." (PMID 41388520, 2025). "The genes, ZWINT, E2F1, HMGB2, KPNA2, and CKS2, were expressed at low or moderate levels in non-tumor tissues." (PMID 31695969, 2019). "Five genes namely ZWINT, CDC7, MCM4, MCM2 and MCM6 are proposed from the comprehensive computational analysis which gets affected in neoplasia stage and are responsible for the disease progression." (PMID 30150654, 2018). "ZWINT, HASPIN, and CDCA3 are all expressed in tumor cells to promote proliferation." (PMID 40416783, 2025). "ZWINT expression was found to be significantly upregulated in NSCLC tissues, which might promote tumor progression via activation of the EMT pathway." (PMID 37091844, 2023).
tumor (continued). "Indeed, the present study showed that CCNA2, CEP55, KIF11, KIF4A, and ZWINT were the top five genes that were significantly and positively correlated with CDK1 in all tumor types from the TCGA database." (PMID 35681641, 2022). "Moreover, the expression of ZWINT was found to be significantly correlated with KIFC1 expression, and KIFC1 and ZWINT knockout cells were observed to reduce the tumor formation ability." (PMID 34852139, 2021). "The expression of LMNB1, TK1, ZWINT, and RACGAP1 was positively associated with tumor purity, while no or weak associations were observed for hub genes and infiltrating immune cells in PCa tissue samples." (PMID 31306099, 2019). "ZWINT protein is elevated in HCC tissues and shows correlation with tumor size and number." (PMID 31695969, 2019). "Furthermore, TPX2, ZWINT, UBE2C, CCNB2, CDK1, BUB1, and BIRC5 may orchestrate the stemness, proliferation, and invasion of tumor cells." (PMID 34671679, 2021). "Based on the findings from TIMER, we proposed that LMNB1, TK1, ZWINT, and RACGAP1 are mainly expressed in PCa cells rather than immune cells, and their functions do not relate to immunological regulation of the tumor microenvironment." (PMID 31306099, 2019).
cancer (31 papers, 2009 to 2025). A tumor composed of atypical neoplastic, often pleomorphic cells that invade other tissues. "ZWINT is associated with the regulation of the cell cycle and has been implicated in cancer progression, which often involves inflammatory pathways." (PMID 40362323, 2025). "Additional research discovered that miR-508-3p downregulates ZWINT, a subunit of the mitotic spindle checkpoint and division, previously shown to be associated with cancer progression." (PMID 40650307, 2025). "ZWINT is significantly overexpressed in a variety of cancers and is closely associated with the prognosis of patients with these cancers." (PMID 34852139, 2021). "Among these genes, CDCA5, FOXM1, KIF15, MCM2, and ZWINT were the most reported genes associated with cancer progression, including EOC." (PMID 31708970, 2019). "Among the top downregulated 50 genes, there were other cancer relevant genes such as cell cycle associated (CCNF1, CCNB1, ZWINT), cancer signaling (STK32B, IGF1, FLT1) and splicing associated (HNRNPM, HNRNPU, SRSF1) genes, which are active areas to investigate further." (PMID 38200580, 2024). "As a traditional cell cycle-related gene, the ZWINT gene has been identified to regulate the onset and development of several types of cancers; however, its association with NSCLC remains unknown." (PMID 37091844, 2023). "Although the exact nature of interactions among different kinetochore components in cancer development is largely unknown, recent evidence suggests that ZWINT is overexpressed in different human cancers and is associated with the worst prognosis and early recurrence of cancer." (PMID 37304238, 2023). "The analysis of data from the TNMplot and UALCAN databases revealed a significant correlation between ZWINT transcription levels and both metastasis and cancer stages." (PMID 40591167, 2025). "The immunohistochemical results further elucidated the up-regulated expression of the ZWINT gene in cancer tissues from the perspective of protein levels." (PMID 37091844, 2023). "Overexpression of ZWINT often resulted in abnormal mitosis in human cancers, which is a common feature of most malignancies." (PMID 37185598, 2023). "Combining the histology data from TCGA and GTEx established that ZWINT was significantly overexpressed in several types of human cancers, indicating its significant role in carcinogenesis." (PMID 37091844, 2023). "Immune correlation research revealed a significant relationship between the ZWINT gene and infiltrating immune cells, such as B cells, CD4+ T cells, cancer-associated fibroblasts, CD8+ T cells, macrophages, neutrophils, and NK cells." (PMID 37091844, 2023). "Immunotherapy targeting immune checkpoints is an emerging research area in cancer treatment, and the study results indicated that the ZWINT gene can be used as a predictor of immunotherapy response to a certain extent." (PMID 37091844, 2023). "LINC00460 and LINC00525 were upregulated in LUAD, which improved the levels of FAM111B and ZWINT via hsa-mir-338 sponge, thus promoting the occurrence of cancer." (PMID 35406786, 2022). "LINC00460, LINC00525, FAM111B and ZWINT were upregulated and hsa-miR-338 was downregulated in most cancers." (PMID 35406786, 2022). "The seven DEGs (AURKA, BUB1, CDC6, MAD2L1, NDC80, ZWINT, and TIMELESS) coexpressed only in the LC&OC coexpression network have been associated with the acquisition of the hallmarks of cancer." (PMID 36101460, 2022).